STAT3 (signal transducer and activator of transcription 3)
Diseases named in the same sentence as STAT3 in open-access papers (continued):
Sharing a sentence is not in itself a finding about the gene and the disease.
cancer (continued). "Deregulated STAT3 and STAT5 signaling promotes cancer cell proliferation and survival in conjunction with other core cancer pathways." (PMID 29728695, 2018). "More recently, YMGKI-2, an active component of Antrodia cinnamomea Mycelia, was shown to abrogate ALDH activity, and to abolish cancer-initiating cell properties in HNSCC, through dual STAT3 and Src inactivation." (PMID 30002682, 2018). "IL-22 is another cytokine produced by γδ and Th17 cells that induces Stat3 and MMP9 in cancer cells to increase their motility and, in human pancreatic ductal adenocarcinoma, their metastatic capability." (PMID 30200242, 2018). "IL-6/JAK/STAT3 pathway was shown to activate EMT through upregulation of Twist, N-cadherin and Vimentin in some types of cancer." (PMID 29581838, 2018). "Since STAT3 is an important oncogenic driver of GBM, the identification of these STAT3 regulated pathways in GICs will inform the development of better targeted therapies against STAT3 in GBM and other cancers." (PMID 29774125, 2018). "Thus, examining the levels of STAT3 in colorectal tumors might be a significant indicator of the severity of prognosis and malignancy, and may possibly present a new target for the treatment of cancer." (PMID 30123088, 2018). "In this study, we found stromal cell-derived SPINK1 not only activates Akt/mTOR, Mek/Erk/Stat3 pathways, signaling branches downstream of EGFR, but also generates profound impact on cancer cell transcriptomics." (PMID 30333494, 2018). "IL-6 also activates STAT-3 to promote VEGF protein expression, angiogenesis, and the growth of cancer cells." (PMID 29794990, 2018). "Currently, anti-BMP1 inhibitors are available, and STAT3 and TGF-β inhibitors are being tested for their efficacy against a variety of cancers in clinical trials." (PMID 29720137, 2018). "We assumed EGF and HGF as inputs into the model, while activities of STAT3 and ERK indicated by their phosphorylated levels are considered as the main model outputs, which together regulate cancer cell proliferation and survival." (PMID 29920512, 2018). "Although STAT3 directly activates the transcription of MMP2 and MMP9 in cancer cells, the regulatory mechanisms in alveolar macrophages should be further validated." (PMID 30410547, 2018). "Therefore, STAT3 could be considered as an important target for cancer treatment." (PMID 29963272, 2018). "ROS, highly produced in cancer cells including PEL, are essential for their survival since sustain the activation of STAT3 as well as of other oncogenic pathways." (PMID 29179721, 2017). "To that end, we focused on STAT3, since this transcription factor is a CCT client protein, is constitutively active in many tumors, and is a predictor of poor prognosis in cancer." (PMID 29299146, 2017). "In contrast, SRVF considerably suppressed the phosphorylation of STAT3, indicating that SRVF induced death of cancer cells by MAPK activation and STAT3 inactivation." (PMID 29038437, 2017). "Current studies have shown that signal transducer and activator of transcription 3 (STAT3) is a definitive link between inflammation and cancer transformation." (PMID 28061445, 2017). "In vitro recapitulation of the TME revealed increased Stat3 phosphorylation in breast epithelial (MCF10A) and cancer cells (SK-BR-3, MCF7, T47D) upon incubation with conditioned medium (CM) of MSCs overexpressing miR-1246." (PMID 28159925, 2017). "It’s worth noting that some cancer stem cell factors, such as Nanog homeobox (NANOG), are well-known targets of STAT3 signaling pathway, further elucidating the regulatory role of STAT3 signaling in the maintenance of CSCs." (PMID 28750679, 2017). "Among them, STAT3 and STAT5 are activated in a large number of human cancers and play major roles in proliferation, apoptosis, and angiogenesis." (PMID 28608828, 2017). "STAT3 and STAT5 are upregulated in numerous types of cancer cells and promote cancer growth, angiogenesis and metastasis." (PMID 28881698, 2017).
cancer (continued). "Altogether, our results show that enhanced STAT3 activity achieved upon RIP4 down-regulation promotes the expression of ECM remodeling genes such as LOX, which contributes to cancer cell de-differentiation and metastasis." (PMID 28574510, 2017). "Our experiments showed that IL-6 treatment induced STAT3 and Chk2 activation and attenuated CREB/ATF-1 phosphorylation in MUC2-silenced HT-29 cancer cells." (PMID 28725043, 2017). "Signal transducer and activator of transcription 3 (STAT3) is also a key player of inflammation and cancer." (PMID 28903349, 2017). "Constitutive over-activation of STAT3 and constitutive expression of PL2L60 have been demonstrated in various types of human cancers." (PMID 28545024, 2017). "Next, we questioned how TM4SF4 activates the JAK2/STAT3 pathway or SRC/FAK/STAT3 pathway, which also reinforces EMT or CSC-like properties of cancer cells." (PMID 29254164, 2017). "Signal transducer and activator of transcription 3 (STAT3) is a transcriptional factor and one of the most frequently activated STAT family members in human cancers." (PMID 28654902, 2017). "Recent studies revealed that signal transducer and activator of transcription 3 (STAT3) is constitutively activated and involved in the process of apoptosis resistance in many malignant tumors." (PMID 28085115, 2017). "Thus, the strategy to target Stat3 signaling may be beneficial for cancer therapy." (PMID 29133922, 2017). "As expected, the phosphorylated states of STAT3 were markedly inhibited by WP1066 and S3 l-201, so as the cancer stem cell markers Nestin, SSES-1, and NANOG." (PMID 29284440, 2017). "Several studies have shown that SB induces cancer cell apoptosis by regulating the AKT, Signal transducer and activator of transcription 3 (STAT3), ERK, JNK and P38 pathways." (PMID 29312612, 2017). "The IL-6/STAT3 signaling pathway plays an important role in the regulation of stemness, EMT, and metastatic dissemination of cancer cells." (PMID 29228728, 2017). "Recent studies reported that CXCR4 induced cancer cell migration and invasion by activating AKT, ERK, Jak2, and Stat3." (PMID 29069741, 2017). "Due to the role of STAT3 in tumorigenesis and the abnormal activation of the pathway in several cancer types including GBM, the JAK2/STAT3 pathway has attracted considerable attention as a potential novel therapeutic target." (PMID 29253028, 2017). "Here, we report that TTB inhibits cancer growth by promoting ROS-mediated inhibition of STAT3 signaling and inducing DNA damage, thereby suggesting that TTB is useful for the treatment of cancer." (PMID 28245605, 2017). "The mechanism is promoted by an S1P/S1P1-dependent increase in signal transducer and activator of transcription 3 (STAT3) and IL-6 formation; this S1P1 dependent pro-inflammatory pathway was first, demonstrated in cancer cells." (PMID 28241498, 2017). "Signal transducer and activator of transcription 3 (STAT3), which mediates cellular responses to interleukins and many other growth factors, is aberrantly activated in the majority of cancers." (PMID 28423603, 2017). "Core-analysis of the altered miRNAs identified top scoring networks of interacting miRNA, which interplay through several genes and molecules known to be involved in cancer and EMT including STAT3, CEBP/β, RUNX1, VEGF and TGF-β." (PMID 28423669, 2017). "IL-6/STAT3 signaling can effectively trigger EMT action and expand the cancer stem cells population in several types of tumors." (PMID 29383101, 2017). "For example, miR-18a impairs cancer cell growth via inhibition of the expression of CDC42 gene, or negatively regulates the expression of PIAS3, an inhibitor of STAT3." (PMID 28718798, 2017). "We further studied the functional relationship between cancer cells and fibroblasts and found that conditioned media from HCC‐ZEB1 and MDA‐231‐D cells upregulated phosphorylated STAT3 in IMR90 and WI38 human fibroblasts." (PMID 28618162, 2017).
cancer (continued). "Previous studies have shown that CXCR2 can be activated by CXCL5 or other ligands to stimulate cancer progression through the activation of downstream pathways, such as JAK/STAT3, JNK, PI3K/AKT and ERK1/2 pathway." (PMID 28356111, 2017). "We then analyzed the expression of G6PD and p-STAT3 in human RCC and paired adjacent non-cancer renal tissues (n=10) by immunohistochemistry." (PMID 29312589, 2017). "In our previous study, we found that SC-43 induced cancer cell apoptosis through upregulation of SHP-1 and downregulation of p-STAT3, suggesting that SHP-1 is a target of SC-43." (PMID 29029413, 2017). "Together, the evidence to date suggests that inhibition of EZH2 suppresses the functions of STAT3 signals involved in CSC maintenance, supporting that EZH2 can be regarded as a target for cancer therapy." (PMID 28415635, 2017). "In particular, activation of STAT3 leads to expression of interleukin-6 and COX-2 which mediate cancer-promoting immunity." (PMID 28881698, 2017). "By inhibiting STAT3, RNA-dependent protein kinase R (PKR), an eukaryotic initiation factor 2alpha (eIF2α) kinase, decreases HIF-1α and VEGF expression in cancer cells." (PMID 28978186, 2017). "Our findings suggested that pantoprazole can alleviate cancer cachexia skeletal muscle wasting by inhibiting the inflammatory response and blocking the JAK2/STAT3 or ubiquitin proteasome pathway." (PMID 28489606, 2017). "According to previous reports, chronic inflammation was suggested to promote cancer development by inducing the COX-2/PGE2 pathway and activating NF-κB and Stat3 signals." (PMID 28472126, 2017). "This pathway involves important key molecules STAT3, AKT and ERK and NF-kB, which are important in cancer cell survival, proliferation, migration and invasion." (PMID 27213582, 2017). "Among these pathways are some key pathways that regulate cancer progression, including the PI3K/AKT, STAT3, MEK/ERK, JNK, FAK, Paxillin, and p130cas pathways." (PMID 29132432, 2017). "STAT3 is a member of the STAT family with important roles in cellular transformation, proliferation, inflammation, and metastasis of cancer." (PMID 29029463, 2017). "In this study, we report the mode of STAT3 inhibition by BENDA both in cell-free system and cancer cells." (PMID 28125678, 2017). "Activated STAT3 also up-regulates BIRC5, a highly-expressed gene in many cancers and whose product (survivin) inhibits apoptosis of cancer cells." (PMID 28747781, 2017). "Together, STAT3 activation is crucial for HIF-1 α and VEGF expression in cancer cells under hypoxia." (PMID 28978186, 2017). "Due to their oncogenic potential STAT3, STAT5, and STAT6 are attractive targets for therapeutic intervention and STAT inhibitors are in development as anti-cancer drugs." (PMID 28903353, 2017). "HGF-induced MET activation also triggers multiple pro-survival pathways in cancer cells, such as AKT and STAT3, promotes epithelial-mesenchymal transition (EMT), and thus confers primary and acquired resistance to anti-cancer therapy." (PMID 28420162, 2017). "STAT3, a downstream target of JAK-3, is required for the proliferation and self-renewal of cancer stem cells." (PMID 28289331, 2017). "Evidence suggest that STAT3 and STAT5 play critical roles in cancer progression, thus making themselves as therapeutic targets." (PMID 29156772, 2017). "STAT3, a member of the STAT protein family, is constitutively activated in a series of human carcinomas, including CRC, and plays a crucial role in proliferation, survival, metastasis, and angiogenesis in cancer." (PMID 29242509, 2017). "Some previous studies have shown that UA can inhibit several cancer cells through multiple pathways, namely NF-κB, ASK1-JNK, STAT3, JNK and TGF-β1/miR-21/PDCD4 Pathways, and so on." (PMID 27708244, 2016).
cancer (continued). "The prominence of STAT3 and STAT5 in cancer is interesting because the sole Drosophila STAT homolog is most like STAT3 and STAT5 in sequence and activity among the seven mammalian STATs." (PMID 27584613, 2016). "Evolving evidences implicate that STAT3 activation is involved in MMP-9 expression and matrix remodeling and thus confers enhanced invasion ability in drug-resistant cancer cells." (PMID 27793010, 2016). "Inhibiting STAT3/5 activity with SH-4-54 in conjunction with further raising intracellular ROS levels beyond the cellular detoxification capacity while simultaneously affecting the SUMO pathway may be a viable therapeutic strategy to target treatment-resistant cancer cells." (PMID 27513743, 2016). "Our previous data have indicated that the potency of LLL12 was higher than that of previously reported STAT3 inhibitors (such as LLL3, WP1066, Stattic, and S3I-201) in human cancer cells." (PMID 26883202, 2016). "One of the anti-cancer mechanisms of ONA was revealed to be mediated by the inhibition of STAT3 activation, and ONA also enhanced the anti-cancer effect of anti-cancer drugs." (PMID 27404320, 2016). "We found a significant correlation between cancer cell migration and SHP-1/p-STAT3/VEGF-A expression in human TNBC cells." (PMID 27364975, 2016). "It is known that BCPO alters several key pathways for cancer development, such as MAPK, PI3K/AKT/mTOR/S6K1, and STAT3 pathways." (PMID 27696789, 2016). "Among the intrinsic pathways, an important role is displayed by developmental signals such as Wnt, Hedgehog, Janus kinase 2-signal transducer and activator of transcription 3 (JAK2-STAT3) and Notch pathways that are frequently deranged in cancers." (PMID 26556856, 2016). "Previous work from our laboratory has shown that UA can inhibit signal transducer and activator of transcription 3 (STAT3) and nuclear factor (NF)-κB activity and can induce apoptosis in cancer cells by upregulating death receptors." (PMID 26909608, 2016). "Our results showed that IL-6 stimulated STAT3 phosphorylation on tyrosine 705 in DLD1 and Hep3B cancer cells." (PMID 26883202, 2016). "Statins are known to reduce cell proliferation via down-regulation of critical signaling pathways in a few human cancers, including AKT/mTOR, MAPK, JAK2/STAT3, Ras, NF-κB, JUNK and RhoA/ROCK pathways." (PMID 26503475, 2016). "Activation state, typically phosphorylation at Y705, expression of STAT3 and presence of nuclear STAT3 have been examined in EBV-related cancers." (PMID 27458446, 2016). "Using a fluorescent probe of S3I-201, the effect on STAT3 protein, as well as the global effect on MDA-MB-231 cancer cells was determined." (PMID 26942696, 2016). "It has been reported that various signals including MAPK, STAT3, or PI3K are relevant to PD-L1 expression; however, the contribution of each signal is inconsistent among different cancers." (PMID 27846317, 2016). "Inhibition of STAT3 and STAT5 signaling has been shown to arrest the growth of several cancer models 3, and cancer cells are more dependent on STAT activity than normal cells." (PMID 27367207, 2016). "By activating downstream Janus kinase (JAK) signal transducer and activator of transcription-3 (STAT3) signaling, IL-6 promotes cancer cell proliferation, survival, and metastatic dissemination." (PMID 27006530, 2016). "Another example is transcription factor STAT3 (signal transducer and activator of transcription 3), which has been shown to have critical roles in EMT induction in a variety of human cancers." (PMID 26901232, 2016).
cancer (continued). "We conclude that the novel small-molecule inhibitor AC-73 inhibits HCC mobility and invasion, probably by disrupting CD147 dimerization and thereby mainly suppressing the CD147/ERK1/2/STAT3/MMP-2 pathways, which are crucial for cancer progression." (PMID 26882566, 2016). "It has been previously shown that GL is a dual NF-κB /STAT3 inhibitor, but nothing is known about its effects on cell cycle and DDR signaling in cancer cells." (PMID 26683224, 2016). "Treatment of bulk cancer cells with PP2A inhibitors, OA27 and CA28, increased S727 phosphorylation of STAT3 in a dose-dependent manner." (PMID 27306323, 2016). "Growth arrest is accompanied by suppressing survival RTKs, including ErbB members and c-Met, as well as their STAT3, IRS and Akt transducers that serve as resistance nodes upon treating B-Raf(V600E) cancers with B-Raf(V600E) kinase inhibitors." (PMID 26959890, 2016). "In cancer, EGFR has been shown to have growth inhibitory effects as it induced the expression of IRF-1 via phosphorylation of STAT1 and STAT3." (PMID 26881744, 2016). "Specifically, loss of ESE3/EHF leads to upregulation of IL-6 and activation of the JAK/STAT3 pathway with consequent induction of EMT and expansion of the cancer stem cell compartment." (PMID 27732936, 2016). "The interactions of HEY2 with Stat3 and Id4 that play important roles in tumorigenesis, also confirm the oncogenic role of HEY2 in human cancers." (PMID 27191260, 2016). "In many forms of cancer the signal transducer and activator of transcription 3 (STAT3) transcription factor remains constitutively active, driving cancer survival and progression." (PMID 27793003, 2016). "Other pro-survival pathways known to be active during progression of cancer include MAPK (ERK, JNK, p38) and STAT3." (PMID 26975752, 2016). "In the metastatic prostate tumor MYC is downregulated due to STAT3-induced transcriptional suppression, however there are reports indicating that STAT3 can also upregulate MYC in different kinds of cancer through IL6." (PMID 28005952, 2016). "Like STAT3, STAT5 has been also shown to regulate proliferation and inhibition of apoptosis in several cancer cells because cyclin D1 and bcl-xL promoters contain putative STAT5 binding sites." (PMID 26911335, 2016). "On the one hand, when expressed in cancer cells and MDSC precursors, SOCS3 can promote antitumor immunity by blocking the effects of STAT3-inducing, immunosuppressive cytokines." (PMID 27148255, 2016). "STAT3 and STAT5 control the expression of numerous genes related to cancer cell metabolism, proliferation, and survival, integrating signals from diverse extracellular stimuli including cytokines, growth factors, hormones, and ROS." (PMID 27513743, 2016). "STAT3 is also activated by RTKs, such as the epidermal growth factor receptor (EGFR) and VEGFR, cytoplasmic kinases, such as Src, as well as some cancer therapies, such as ionizing radiation (IR)." (PMID 27148255, 2016). "It has been shown before that STAT3-specific signaling can inhibit PDH and thus block pyruvate oxidation through PDH in primary fibroblasts and cancer cell lines." (PMID 26679997, 2016). "STAT3 and STAT5 are therefore intricately and complexly involved in oxidative metabolism in cancer cells, although literature conflicts regarding their regulation by ROS as well as their influence on ROS production." (PMID 27513743, 2016). "The relationship between STAT3 and EGF is originally found in mouse liver, and is usually observed in cancer/tumorigenesis." (PMID 27096934, 2016). "Several signal transduction pathways such as STAT3, PI3K/AKT/NF-κB cascade, p38/MAPK/ERK, or the AMPK pathways play an important role in inflammation-mediated response at all stages of cancer development and refractoriness to chemotherapy." (PMID 26762586, 2016).